LIF (LIF interleukin 6 family cytokine)
Diseases named in the same sentence as LIF in open-access papers (continued):
Sharing a sentence is not in itself a finding about the gene and the disease.
glioma (37 papers, 2012 to 2025). A benign or malignant brain and spinal cord tumor that arises from glial cells (astrocytes, oligodendrocytes, ependymal cells). "Decreased levels of sIL10RB (OR=0.69, 95% CI=0.55-0.87) and Leukemia inhibitory factor (LIF) (OR=0.47, 95% CI=0.23-0.94) was associated with glioma 5 or less years before diagnosis." (PMID 37265788, 2023). "The inverse association between leukemia inhibitory factor (LIF) and glioma is restricted to participants whose blood was drawn five years before glioma diagnosis." (PMID 28594935, 2017). "LIF was associated with decreased glioma risk within five years before glioma diagnosis (odds ratio (OR) = 0.47, 95% confidence interval (CI) = 0.23, 0.94)." (PMID 28594935, 2017). "Our observation of decreased glioma risk with higher levels of LIF was unexpected because this cytokine is a mediator of glioblastoma stem cell renewal and a post- diagnostic case-control study of serum cytokines found higher levels of this cytokine among glioma cases than among controls." (PMID 28594935, 2017). "We initially examined the secretion of the LIF cytokine in CM of a collection of human Glioma-Initiating Cells (GICs) derived from both adult and pediatric tumors using a LIF-specific ELISA test, as outlined in Materials and Methods." (PMID 38137514, 2023). "LIF is an autocrine growth factor for germ cell tumor cells and mediates self-renewal of glioma cells and mouse models." (PMID 35204717, 2022). "LBX2.AS1 has been reported to sponge miR-491-5p to further upregulate LIF and modulate the progression of glioma." (PMID 36033510, 2022). "Transforming growth factor beta (TGF-β) activates the LIF promoter located at −276/−73 to increase self-renewal in glioma-initiating cells via Smad2/3/4." (PMID 35740622, 2022). "In glioma cell cultures, LIF treatment doubled the amount of CD133 positive cells, and prevented cell differentiation." (PMID 35204717, 2022). "We then performed IHC on a tissue microarray containing 169 glioma cases to evaluate the prognostic significance of LIF and CCL2." (PMID 34987659, 2022). "Collectively, LBX2-AS1 and miR-491-5p regulated the expression of N-cadherin, E-cadherin and Vimentin in glioma cells by the LIF/STAT3 axis." (PMID 34729101, 2021). "TGFb also induces expression of LIF mRNA; LIF induction is important to maintain the self-renewal of glioma-initiating cells and prevent their differentiation." (PMID 30899759, 2019). "LIF has been reported to play an essential role in inducing the self-renewal capacity of glioma-initiating cells and thus promoting oncogenesis." (PMID 26390214, 2015). "TGFβ1 increased glioma-initiating cells (GICs) self-renewal through the induction of LIF and the JAK-STAT pathway, and TGFβ inhibitors were emerging as compounds targeting GICs." (PMID 25978454, 2015). "For example, Smad interacting protein 1 (SIP1), TGF-beta, and LIF have been identified and play an essential role in glioma." (PMID 24565222, 2013). "Here, we demonstrate that the combination of IL-1β and TGF-β can promote self-renewal and oncogenic capability of glioma cells by inducing expression of stemness factor genes Bmi-1, LIF and Notch-2." (PMID 22330721, 2012). "Knockdown of LIF significantly reduced nuclear level of phosphorylated STAT3 in glioma cells." (PMID 34729101, 2021). "Taken together, serving as a miR-491-5p sponge, LBX2-AS1 upregulated LIF in glioma cells." (PMID 34729101, 2021). "Our previous demonstration that ZEB1 is a negative regulator of LIF, a gene that induces glioma stem cell propagation, suggests that the deletion of ZEB1 may impart more stemness to tumors that lose ZEB1 expression." (PMID 30705664, 2018). "We found three positive (VEGF, beta-Catenin and C-C motif chemokine 22 (CCL22)) and two negative (LIF, sIL10RB) associations between five prediagnostic serum cytokines and the subsequent risk of glioma." (PMID 28594935, 2017).
glioma (continued). "Furthermore, TGFβ drives the expression of LIF through SMAD-mediated transcription in glioma-initiating cells." (PMID 27586372, 2017). "Moreover, the self-renewal of glioma-initiating cells is achieved by the LIF/STAT3 signaling." (PMID 34729101, 2021). "Inflammatory and glioma cells express and can release SP that regulates neurogenic inflammation mediated by the release of IL-1β, IL-6, IL-8, TNF-α, GM-CSF, and LIF." (PMID 39941886, 2025). "Quantitative PCR and immunohistochemical analysis showed that LIF, LOX, MMP9, S100A4, SRPX2, and TIMP1 were expressed at high levels in glioma, whereas SLITI1 and SMOC1 were expressed at low levels, consistent with our previous results." (PMID 36560848, 2023). "Survival analysis using our own glioma tissue microarray and four GBM databases consistently showed that LIF and CCL2 predicted poor survival of GBM patients." (PMID 34987659, 2022). "GDF15 can successively activate the ERK pathway, increase LIF expression through c-Fos binding to the LIF promoter region (−685/−792), and then promote the phosphorylation of STAT3, thus expanding the stemness of glioma cells." (PMID 35740622, 2022). "LIF and CCL2 have been found to be involved in glioma 39, 55, 56, but their relationships with molecular subtypes of GBM have not yet been described." (PMID 34987659, 2022). "It exerts the sponge effect on miR-491-5p, thus upregulating LIF and activating the LIF/STAT3 axis for promoting proliferation and EMT in glioma." (PMID 34729101, 2021). "Previous researches have uncovered high level of LIF was correlated to proliferation and EMT in glioma, which was further supported by the findings from CCK-8, colony formation and Transwell assays in our study." (PMID 34729101, 2021). "The subsequent activated LIF/STAT3 signaling was responsible for promoting proliferation and EMT in glioma." (PMID 34729101, 2021). "We have confirmed a ceRNA network involving the LBX2-AS1/miR-491-5p/LIF axis in regulating proliferation and EMT of glioma." (PMID 34729101, 2021). "We show that conditioned media from the selection of adult but not pediatric Glioma-Inducing Cells (GICs) maintain mESCs’ pluripotency in correlation with LIF secretion and activation of STAT3 protein." (PMID 38137514, 2023). "In other cancer types, including glioma and HCC, LBX2-AS1 affects cell proliferation and apoptosis through the miR-491-5p-leukemia inhibitory factor (LIF)-signal transducer and activator of transcription 3 (STAT3) and miR-384-insulin receptor substrate 1 (IRS1) pathways, respectively." (PMID 36131071, 2023). "The chromatin at the LIF locus exhibited a conformation consistent with active transcription, LIF mRNA was increased, and phosphorylated Stat3 (pStat3) was increased, which supported the upregulation of the LIF and the downstream JAK/STAT pathway in H3.3-G34R/V mutant gliomas." (PMID 37509641, 2023). "In addition, cachexia models that are mediated by highly expressed LIF include the intracerebral injection of human OVCAR3 ovarian carcinoma, A431 epidermoid carcinoma, and GBLF glioma cells in mice." (PMID 35740622, 2022). "Moreover, LBX2-AS1 depletoin not only downregulated LIF and p-STAT3 in glioma cells, but also affected the protein levels of N-cadherin, E-cadherin and Vimentin." (PMID 34729101, 2021). "LIF activates JAK/STAT signalling, promoting glioma cell self-renewal." (PMID 27586372, 2017). "Strikingly, a relevant research demonstrates that TGF-β and leukemia inhibitory factor (LIF) are responsible for the formation of neurospheres and the self-renewal ability of glioma-initiating cell (GICs) and that the effect of TGF-β is dependent on induction of LIF and JAK-STAT pathway." (PMID 23616948, 2013).
melanoma (37 papers, 2013 to 2025). A malignant, usually aggressive tumor composed of atypical, neoplastic melanocytes. "To date, elevated expression of LIF has been associated with poor prognosis and distant metastasis in breast cancer, malignant melanoma, colorectal cancer, and pancreatic cancer." (PMID 41163398, 2025). "Using the coefficients obtained by multivariate Cox analysis, the risk score of melanoma patients was calculated according to the following formula: risk score = (−0.097) × A2M + (−0.185) × NAMPT + (−0.123) × LIF + (−0.247) × EBI3 + (−0.170) × ERAP1." (PMID 35326741, 2022). "In melanomas, LIF can induce osteoclastogenesis and is associated with significantly greater incidence of metastasis to bone in mouse models." (PMID 35204717, 2022). "By comparing with available cancer mutation data extracted from cBioportal database, we further observed other LIF mutations residing within the signal peptide region in the melanoma studies." (PMID 30504771, 2018). "Melanomas have been reported to express high level of LIF and LIFR, which are associated with poorer prognosis." (PMID 30504771, 2018). "The induction of ILEI and LIFRβ expression by TGF-β is particularly interesting result, as TGF-β has been associated with the increased transcription of LIF in a number of cancers including in melanoma, thymic epithelium, glioblastoma, and in tumor associated stromal fibroblasts." (PMID 34395259, 2021). "In addition, the TGFβ/LIF/p21 axis caused melanoma cell cycle arrest in the G1 phase and cell death mediated by caspase." (PMID 34068679, 2021). "In this study, six genes (ADCYAP1R1, GPI, IFITM1, KIR2DL4, LIF, and NTS) were identified as being closely associated with prognosis among a pool of 1793 melanoma-related genes." (PMID 38217549, 2024). "Six genes closely associated with the prognosis of melanoma patients, including ADCYAP1R1, GPI, IFITM1, KIR2DL4, LIF and NTS, were elected to fabricate a prognosis model." (PMID 38217549, 2024). "GABA-A receptor–positive keratinocytes were found to mediate their protumorigenic effect by upregulating MYCN, a known upstream activator of LIF expression, and by secreting LIF, which in turn increases melanoma cell proliferation." (PMID 39201498, 2024). "Melanoma-derived factors, namely leukemia inhibitory factor (LIF), controlled JunB upregulation through Janus kinase (JAK)/signal transducer and activator of transcription 3 (STAT3) signaling." (PMID 37894348, 2023). "Serine 727 phosphorylation is induced by IFNα/γ in several human malignant melanoma lines and bone marrow-derived mesenchymal stem cells, activating the LIF/ERK/pSTAT3 S727 axis, and promoting melanoma metastases." (PMID 36672229, 2023). "Melanoma-derived LIF reprogrammed the molecular and functional phenotype of LIFR-expressing microglia cells." (PMID 37894348, 2023). "Autophagy secreted proteins, such as IL‐1β, CXCL8, LIF, are shown to be elevated in high‐autophagy melanoma cell lines." (PMID 36124714, 2022). "LIF has been shown to be strongly expressed in melanoma cell lines and contributes to increased attachment, proliferation and migration." (PMID 35267541, 2022). "It has been shown in vitro that the reduction effect of TGF-β on melanoma growth was mediated by LIF." (PMID 34068679, 2021). "LIF is frequently upregulated in different types of human tumors, including nasopharyngeal carcinoma, melanoma, breast, colorectal and lung cancers." (PMID 32651426, 2020). "For instance, siRNA-mediated suppression of LIF restricted proliferation, attachment, migration, and colony formation of human melanoma cells." (PMID 32651426, 2020). "Considering the similar alterations of LIF/LIFR between NPC and melanoma, systemically analyzing the omics data of these two cancers will provide insightful information regarding to the role of LIF/LIFR in cancers." (PMID 30504771, 2018). "Our results clearly indicate that LIF inhibits melanoma cell growth downstream of the TGFβ signaling pathway." (PMID 25885043, 2015).
melanoma (continued). "Consistently, we show here that LIF itself also contributes to prevention of tumor metastasis in melanoma, by mediating the TGFβ inhibitory effects on cell migration." (PMID 25885043, 2015). "LIF signaling is expressed at elevated levels in a broad range of human cancers, including melanoma." (PMID 26329521, 2015). "Our results indicate that both p21 and LIF play an important regulatory role downstream of TGFβ in regulating melanoma growth inhibition." (PMID 25885043, 2015). "We found the leukemia inhibitory factor (LIF) to be strongly up-regulated by TGFβ in melanoma cells, defining LIF as a novel TGFβ downstream target gene in cutaneous melanoma." (PMID 25885043, 2015). "Our study defines a novel regulatory pathway mediated by the TGFβ/LIF/p21 signaling axis that controls tumor formation and tumor progression in melanoma." (PMID 25885043, 2015). "LIF modifies melanoma cell capacity to adhere to matrix components by upregulation of integrin expression." (PMID 26329521, 2015). "We found that LIF mediates both TGFβ-induced G1 arrest and apoptosis in melanoma, indicating a tumor suppressor-like role for this cytokine." (PMID 25885043, 2015). "Collectively, our results indicate that the TGFβ/LIF/p21 signaling axis plays a major role in controlling tumor formation and tumor progression in melanoma." (PMID 25885043, 2015). "LIF was recently reported for regulating stemness transcription factors, including Nanog and Oct4, in malignant melanoma." (PMID 26296968, 2015). "Having highlighted the TGFβ/LIF pathway as a potent tumor suppressor in melanoma, we then assessed the clinical relevance of these findings." (PMID 25885043, 2015). "To further understand how TGFβ/LIF regulate growth inhibition in melanomas, we examined the expression levels of several cell cycle regulators that have been shown to be involved downstream of TGFβ-mediated growth arrest in other tissues." (PMID 25885043, 2015). "Our findings indicate that ADCYAP1R1, GPI, and NTS may contribute to a poor prognosis in melanoma patients, while IFITM1, KIR2DL4, and LIF are more likely to be associated with a better prognosis in individuals with melanoma." (PMID 38217549, 2024). "LIF has also been known as Human Interleukin for DA cells, Cholinergic Differentiation Factor, Differentiation Inhibitory Activity, Hepatocyte Stimulating Factor, and Melanoma-Derived LPL Inhibitor." (PMID 35204717, 2022). "BMP4 is known to be regulated by LIF (leukemia inhibitory factor), which might be involved in melanoma-induced bone metastasis." (PMID 34073664, 2021). "LIF is also produced in melanoma cells and is overexpressed in comparison to melanocytes." (PMID 34068679, 2021). "CAF-derived LIF induces nasopharyngeal carcinoma tumor growth, promotes the migration and invasion of tumor cells in oropharyngeal carcinomas and melanoma, stimulates angiogenesis in colon cancer, and induces chemoresistance in esophageal squamous cell carcinoma." (PMID 34947829, 2021). "Furthermore, mice research provided evidence that LIF regulated the development of cachexia in melanoma and bone metastasis probably through stimulation of osteoclastogenesis." (PMID 34068679, 2021). "Moreover, overexpression of LIF has been observed most frequently in many types of cancers, such as colorectal, lung, breast, melanoma and nasopharyngeal, head and neck cancer." (PMID 29899555, 2018). "For instance, amoeboid melanoma cells support contractility, establishing a positive feedback loop with the cytokines leukemia inhibitory factor (LIF)/IL6 and the Janus kinase (JAK)/signal transducer and activator of transcription (STAT) pathway to maintain Rho-ROCK activity." (PMID 27158478, 2016). "Thus, our results define LIF signaling as a potent tumor suppressor and as a potential suppressor of metastasis in human melanoma." (PMID 25885043, 2015). "Melanomas produce higher levels of LIF and POMC, suggesting LIF may stimulate melanoma growth in part by promoting HPA axis peptides." (PMID 26329521, 2015).
melanoma (continued). "We thus investigated whether LIF signaling might also play such a role in melanoma, by regulating the TGFβ-mediated inhibition of migration and invasion." (PMID 25885043, 2015). "Together, our results define the LIF/p21 signaling cascade as a novel tumor suppressive-like pathway in melanoma, acting downstream of TGFβ to regulate cell cycle arrest and cell death, further highlight new potential therapeutic strategies for the treatment of cutaneous melanoma." (PMID 25885043, 2015). "Our results define LIF as a novel target downstream of TGFβ in melanoma cell lines and indicate that TGFβ-induced expression of LIF is a prerequisite for the TGFβ tumor suppressive effects, including cell cycle arrest and apoptosis as well as the inhibition of cell migration." (PMID 25885043, 2015). "Since LIF signals through formation of heterodimers between a specific LIF receptor (LIFr) and the common IL-6 family co-receptor gp130, a strong rationale exists to investigate the expression and potential role of LIFr in melanoma tumorigenesis." (PMID 26329521, 2015). "Our results highlight LIF as a TGFβ target gene in melanoma, suggesting that it may play a role downstream of TGFβ-mediated growth inhibition in melanoma." (PMID 25885043, 2015). "Constantly enhanced expression of LIF in skin cancers, including melanoma, have been reported." (PMID 26329521, 2015). "Therefore, we focused on the LIF/LIFR axis and demonstrated (in three out or four MBM cell lines used in this study) that microglial LIFR activation by LIF in melanoma-exposed microglia induces downstream signaling of the JAK/STAT3 pathway, leading to JunB upregulation." (PMID 37894348, 2023). "However, decreased expression of LIF reduced bone morphogenetic proteins 4 and 7, which may in part be because of involvement in bone metastasis or melanoma-induced bone destruction." (PMID 34068679, 2021). "To evaluate whether the protective potential of LIF against apoptosis was associated with a dedifferentiation of CCA cells to a stem cell-like phenotype, as described for LIF in malignant melanoma, we studied the gene expression of stem cell markers, Nanog and Oct4, following LIF stimulation." (PMID 26296968, 2015). "In this study, six genes (ADCYAP1R1, GPI, IFITM1, KIR2DL4, LIF, and NTS) that exhibited strong correlation with the prognosis of melanoma patients were identified." (PMID 38217549, 2024). "Here, plasma levels of IL-8, CCL4, osteopontin, LIF and BDNF were determined at baseline (T0), after 2 months of therapy (T2) and, when feasible, at progression (TP), in 70 melanoma patients treated with BRAF and MEK inhibitors." (PMID 39143551, 2024). "The immunohistochemical results of the Human Protein Atlas dataset demonstrated that four hub genes (A2M, NAMPT, LIF, and ERAP1) are overexpressed in melanoma tissues." (PMID 35326741, 2022). "Nude mice carrying melanoma G361 and SEKI cells expressing large amounts of LIF show a cachectic state, whereas nude mice carrying A375 and MEWO cells without LIF expression are not cachectic." (PMID 35740622, 2022). "We observed that CXCL1 was predominantly produced by the melanoma cells, while IL6 and LIF were expressed mainly by the fibroblasts and CXCL8 by both cell types." (PMID 33182777, 2020). "TGFβ potently induced LIF expression both at the mRNA and protein levels in WM793B and WM278 cells, suggesting a role for LIF in mediating the TGFβ effects in melanoma cells." (PMID 25885043, 2015). "In particular, this transcriptional regulation involves the JAK/STAT pathway (JAK1, LIF, and IL11), which is a strong regulator of contractility in melanoma." (PMID 26526369, 2015). "Our results support these findings and show that that TGFβ-induced LIF expression through activation of STAT3 further leads to p21 gene transcription and TGFβ-mediated cell cycle arrest and apoptosis in melanoma." (PMID 25885043, 2015).